DDX41 (DEAD-box helicase 41)
Description:
Multifunctional protein that participates in many aspects of cellular RNA metabolism. Plays pivotal roles in innate immune sensing and hematopoietic homeostasis. Recognizes foreign or self-nucleic acids generated during microbial infection, thereby initiating anti-pathogen responses. Mechanistically, phosphorylation by BTK allows binding to dsDNA leading to interaction with STING1. Modulates the homeostasis of dsDNA through its ATP-dependent DNA-unwinding activity and ATP-independent strand-annealing activity. In turn, induces STING1-mediated type I interferon and cytokine responses to DNA and DNA viruses. Selectively modulates the transcription of certain immunity-associated genes by regulating their alternative splicing. Binds to RNA (R)-loops, structures consisting of DNA/RNA hybrids and a displaced strand of DNA that occur during transcription, and prevents their accumulation, thereby maintaining genome stability. Also participates in pre-mRNA splicing, translational regulation and snoRNA processing, which is essential for ribosome biogenesis.
Synonyms: ABS; MGC8828; MPLPF
Tractability: Small molecule: a structure with a bound ligand is known. PROTAC: UniProt records ubiquitination sites on it; ubiquitination databases record sites on it; its protein half-life has been measured.
Target class: Enzyme; Hydrolase
Gene: Protein-coding gene on chromosome 5 (177,511,569 to 177,516,979, reverse strand). Ensembl gene ENSG00000183258.
Subcellular location: Nucleus; Cytoplasm
Subcellular location (Human Protein Atlas): Nucleoplasm; Nucleoli
Pathways (Reactome):
Immune System: IRF3-mediated induction of type I IFN; Regulation of innate immune responses to cytosolic DNA; STING mediated induction of host immune responses
Metabolism of RNA: mRNA Splicing - Major Pathway
Gene Ontology:
Molecular function: ATP hydrolysis activity; protein binding; RNA binding; RNA helicase activity; ATP binding; DNA binding; nucleic acid binding
Biological process: cell differentiation; cell population proliferation; cGAS/STING signaling pathway; mRNA splicing, via spliceosome; apoptotic process
Cellular component: catalytic step 2 spliceosome; cytoplasm; cytosol; membrane; nucleoplasm; nucleus; spliceosomal complex; endoplasmic reticulum
Genetic constraint (gnomAD): Loss-of-function variants: 50 observed, 82.39 expected, observed/expected ratio (o/e) 0.61, 90% interval 0.48 to 0.77. The upper end of that interval is the gene's LOEUF score, 0.77, which puts it in group 3 of 6, group 1 being the genes least tolerant of losing a copy. Missense variants: 633 observed, 890.45 expected, observed/expected ratio (o/e) 0.71, 90% interval 0.67 to 0.76. Synonymous variants: 381 observed, 341.55 expected, observed/expected ratio (o/e) 1.12, 90% interval 1.02 to 1.21.
Gene-disease validity (ClinGen):
ClinGen rates the evidence that DDX41 causes each of these diseases.
DDX41-related hematologic malignancy predisposition syndrome (autosomal dominant): Definitive. Any hereditary neoplastic syndrome in which the cause of the disease is a mutation in the DDX41 gene.
Homologues: Orthologues: chimpanzee DDX41 (99% identical), rat Ddx41 (99% identical), mouse Ddx41 (99% identical), macaque DDX41 (99% identical), pig DDX41 (99% identical), guinea pig DDX41 (98% identical), rat Ddx41l1 (96% identical), tropical clawed frog ddx41 (89% identical), rabbit DDX41 (85% identical), Drosophila melanogaster abs (65% identical), Caenorhabditis elegans sacy-1 (54% identical). Paralogues in human: DDX46 (30% identical), DDX17 (30% identical), DDX3X (30% identical), DDX42 (30% identical), DDX5 (30% identical), DDX3Y (29% identical), DDX23 (29% identical), DDX43 (28% identical), DDX4 (28% identical), DDX53 (27% identical), DDX59 (26% identical), DDX21 (24% identical), and 26 more.
Diseases named in the same sentence as DDX41 in open-access papers:
DDX41 is named in the same sentence as 78 diseases in open-access papers, as found by Europe PMC text mining. Sharing a sentence is not in itself a finding about the gene and the disease. The quoted sentences say what the papers report.
myeloid neoplasm (46 papers, 2016 to 2026). Proliferation of myeloid cells originating from a primitive stem cell. "This systematic review and meta-analysis were conducted to assess the clinical characteristics and relationship between DDX41 mutations and OS in myeloid neoplasm patients." (PMID 40257479, 2025). "Although clinical evidence shows clear pathologic roles of DDX41 germline and somatic mutations in myeloid neoplasms, often leading to DDX41 loss of function, the mechanism remains elusive." (PMID 40764304, 2025). "The mechanism with which mutations in the gene predispose a patient to myeloid malignancies is not completely understood; DDX41 is one of the most commonly mutated genes in those with myeloid malignancies with germline predisposition." (PMID 40407636, 2025). "The most frequent genetic alteration associated with germline myeloid neoplasms is DDX41, accounting for about 80% of cases." (PMID 41464583, 2025). "A comprehensive analysis was undertaken in order to elucidate the association between DDX41 mutations and myeloid neoplasms prognosis." (PMID 40257479, 2025). "Germline DDX41 mutations are linked to myeloid neoplasms, but their roles in the disease is unclear." (PMID 40764304, 2025). "In that study, there were 346 patients with a myeloid neoplasm and DDX41 mutation, of which 11 patients had p.M1| only, 15 had p.Arg525His only, and 24 patients had p.Asp140GlyFs*2 only." (PMID 40407636, 2025). "Despite DDX41 having been recognized as a tumor-inhibitory gene in myeloid neoplasms, several experiments have assessed the predictive value of DDX41 mutations in myeloid neoplasms, yet the results remain inconclusive." (PMID 40257479, 2025). "The DDX41 mutation was identified as the underlying cause in 80% of myeloid tumors with a genetic background, representing 13% of the total cases." (PMID 40257479, 2025). "We have included the most often reported co-mutations in patients who have myeloid neoplasms accompanied by DDX41 mutations." (PMID 40257479, 2025). "Patients with DDX41 mutation who go on to develop myeloid neoplasms often have a germline heterozygous mutation and acquire a somatic mutation in the second DDX41 allele usually in the sixth decade of life." (PMID 40407636, 2025). "Our results substantiate that DDX41 mutations were associated with significantly good OS and provide more insight into the clinicopathological characteristics of DDX41 mutations in individuals with myeloid neoplasms." (PMID 40257479, 2025). "Four studies with data on DDX41 mutation and age of diagnosis of myeloid neoplasms were identified with a total of 6948 patients for analysis." (PMID 40257479, 2025). "Our study contributes to a better understanding of the unique features of DDX41-associated myeloid neoplasms." (PMID 41303035, 2025). "Likely-pathogenic variants were also identified in the ETV6 and DDX41 genes, both of which are key to hematopoiesis in myeloid neoplasms." (PMID 40725152, 2025). "The incidence of DDX41 variants in myeloid neoplasms has been reported to range from 2–5% across various studies, with a pooled incidence of 3.3%." (PMID 41303035, 2025). "Similarities for DDX41 frequency and penetrance values in both DiscovEHR and UKBB provide noteworthy evidence supporting DDX41 as a major driver in myeloid malignancy germline predisposition." (PMID 39501104, 2025). "Heterozygous germline variants in DDX41 are now recognized as the most frequent germline predisposition to adult-onset myeloid neoplasms, particularly myelodysplastic neoplasm (MDS) and acute myeloid leukemia (AML)." (PMID 41303035, 2025). "Despite these advances, the biology and clinical impact of DDX41-mutated myeloid neoplasms are not yet fully understood." (PMID 41303035, 2025). "In the current analysis, p.M1I, p.D140fs and p.R525H are the most common germline DDX41 mutations, which have multiple functions in the pathophysiology of a specific category of myeloid neoplasms." (PMID 40257479, 2025).
myeloid neoplasm (continued). "Mutations in DDX41 account for 2–5% of patients with myeloid neoplasms, with the predominant germline mutations being frameshift, truncation, and missense." (PMID 40407636, 2025). "Although this meta-analysis methodically compiles data emphasizing the critical function of DDX41 mutation as a prognostic factor in myeloid neoplasms, it is imperative to recognize its inherent limitations." (PMID 40257479, 2025). "It was recently shown that up to 13% of myeloid neoplasms have a genetic background, of which DDX41 variants account for about 80% of cases." (PMID 38203823, 2024). "Germline variants of DDX41 are the most prevalent mutations predisposing adults to myeloid neoplasms." (PMID 39185415, 2024). "Truncating mutations in DDX41 have been shown to increase the risk of developing myeloid neoplasms and are associated with faster progression to leukemia." (PMID 39118233, 2024). "Germline monoallelic variants in DDX41, often frame-shift variants in the N-terminal region, have been associated with an increased risk of myeloid malignancies, including MDS and AML." (PMID 39453476, 2024). "Since the first report of DDX41 mutations in myeloid neoplasms, both germline and acquired somatic DDX41 mutations have been identified to define a significant disease entity characterized by late-onset and unique clinical features." (PMID 38514771, 2024). "Mutations in DDX41 have been associated with myeloid neoplasms, including myelodysplastic syndrome and acute myeloid leukemia." (PMID 38348889, 2024). "Recently, myeloid neoplasms with germline DDX41 variants were shown to have a higher proportion of somatic CUX1 variants compared with those without a known germline background." (PMID 38203823, 2024). "Both inherited and sporadic mutations in DDX41 have been identified in patients with myeloid neoplasms." (PMID 39185415, 2024). "Analysis of different subtypes of myeloid neoplasms (MNs) reveals the highest frequency of DDX41 germline variants in secondary AML and high-risk MDS, followed by low-risk MDS, primary AML and MPN." (PMID 39185415, 2024). "We hope that further analysis will allow for a better treatment of the myeloid neoplasm related to DDX41 mutation." (PMID 39526222, 2024). "Previous reports showed that the myeloid neoplasm with the germline DDX41 mutation was slowly progressive and the rate of remission after induction therapy for high-risk MDS/AML with germline DDX41 mutation was high, with a good prognosis." (PMID 39526222, 2024). "In myeloid neoplasms, pathogenic variants in the gene encoding DDX41, a DEAD-box RNA helicase, are found in about 5% of cases." (PMID 38203823, 2024). "Mutations in DDX41 have been associated with myeloid neoplasms (MNs), particularly myelodysplastic syndrome (MDS) and acute myeloid leukemia (AML)." (PMID 38348889, 2024). "Several mechanisms have been proposed for the actions of DDX41 variants in the development of myeloid neoplasms." (PMID 38203823, 2024). "According to the 2016 World Health Organization classification, a germline DEAD-box helicase 41 gene (DDX41) mutation with myeloid neoplasms has been newly classified." (PMID 39526222, 2024). "Both our patients are males who, in presence of DDX41 mutations, are expected to develop myeloid malignancies more frequently than females." (PMID 39118233, 2024). "Inherited forms of myeloid neoplasms have been associated with germline mutations in multiple genes, including DDX41 and SRP7236–38." (PMID 37002311, 2023). "Further data supporting the correlation of rRNA deregulation with myeloid neoplasms indicate the potential role of DDX41, whose germline mutations predispose to myeloid malignancies, in the processing of pre-ribosomal rRNA to mature rRNA." (PMID 37835504, 2023). "The DEAD-box RNA helicase-1 gene (DDX41) is one of the most frequently identified mutations in myeloid neoplasms with a genetic predisposition." (PMID 36672294, 2023).
myeloid neoplasm (continued). "Germline DDX41 variants predispose to myeloid malignancies, most often MDS and AML and to a lesser extent chronic myelomonocytic leukemia (CMML) or myeloproliferative neoplasms (MPNs)." (PMID 37904876, 2023). "This article reviews our current understanding of DDX41 mutations in myeloid neoplasms in pathologic and clinical features and their clinical implications." (PMID 36672294, 2023). "We are rapidly gaining knowledge about hereditary MDS/AML through recent clinical and translational research endeavors, particularly of DDX41-associated hereditary myeloid neoplasms." (PMID 36672294, 2023). "DDX41 is located at 5q35.3, and its mutation has unique features of male predominance and long-term cytopenia before the development of myeloid neoplasms." (PMID 36672294, 2023). "The study further showed that pathologic or likely pathologic germline mutations of DDX41 were identified 10 times more frequently in patients with myeloid neoplasms than the general population." (PMID 36672294, 2023). "In a recently published study using a multi-national cohort, DDX41 germline mutations account for about 80% of patients with myeloid neoplasms with germline predisposition." (PMID 36672294, 2023). "The DEAD-box RNA helicase 41 gene, DDX41, is frequently mutated in hereditary myeloid neoplasms, identified in 2% of entire patients with AML/MDS." (PMID 36672294, 2023). "DDX41 mutations are clinically associated with an increased lifetime risk of myeloid neoplasms, including the early presentation of idiopathic cytopenia of undetermined significance (ICUS)." (PMID 36672294, 2023). "Large cohort studies have shown that 1.5–3.8% of patients with myeloid neoplasms have DDX41 mutations." (PMID 36672294, 2023). "The DEAD-box RNA helicase 41, DDX41, is one of the most frequently identified mutations in myeloid neoplasms with germline predispositions, which represents 2% of the entire MDS/AML population." (PMID 36672294, 2023). "Myeloid malignancies with DDX41 mutations are often associated with bone marrow failure and cytopenia before overt disease manifestation." (PMID 36229594, 2022). "The processes by which the DDX41 mutation contributes to the oncogenesis that leads to myeloid neoplasms (MNs) have been investigated, but the underlying molecular pathogenesis of DDX41 mutations in B lymphoblastic leukemia (B-ALL) has not been revealed." (PMID 35246110, 2022). "Several recent large clinical studies, including a prospective investigation, have established the clinical characteristics of myeloid malignancies with DDX41 mutations." (PMID 36119490, 2022). "This is the case of DDX41, originally classified as one of the most commonly mutated genes in familial myeloid neoplasms, whose variants are now also recognized in hematolymphoid neoplasms, such as T-LGLL and multiple myeloma." (PMID 36358655, 2022). "An additional four CHIP genes (ASXL1, TET2, JAK2, and DDX41) were significantly associated with myeloid neoplasms and are likely driven by somatic alterations." (PMID 36199081, 2022). "DDX41 and various pathogenic germline mutations have newly been recognized as the cause of adult-onset familial leukemia and myeloid malignancies." (PMID 36185231, 2022). "DDX41 mutation has been reported mainly in about 2%–5% of myeloid neoplasms, a few in chronic myeloid leukemia, lymphomas, multiple myeloma, sarcoidosis, and blastic plasmacytoid dendritic cell neoplasm." (PMID 35844724, 2021). "Limited studies have been described DEAD‐box helicase 41 (DDX41) mutations in hematological diseases other than myeloid neoplasms." (PMID 35844724, 2021). "In this study, DDX41 mutations were identified in 0.8% of myeloid neoplasms, 0.9% of acute lymphoblastic leukemia (ALL), and 1.0% of aplastic anemia (AA)." (PMID 35844724, 2021). "In fact, the average age of diagnosis of a myeloid malignancy in those with a germline DDX41 mutation is 65–70 years old, the same as the general population." (PMID 34298596, 2021).
myeloid neoplasm (continued). "Myeloid neoplasms with germline DEAD‐box helicase 41 (DDX41) mutation have been included in the 2016 revised World Health Organization (WHO) myeloid neoplasms classification as a new diagnostic category." (PMID 35844724, 2021). "Mutations of spliceosomes are common in myeloid neoplasms, but are generally mutually exclusive with DDX41 mutations." (PMID 35054439, 2021). "Myeloid neoplasms with germline DDX41 mutations are frequently present with hypocellular bone marrow, erythroid dysplasia, and high-risk MDS or AML." (PMID 35054439, 2021). "Next-generation sequencing screening is a feasible tool to screen unselected myeloid neoplasms for germline DDX41 mutations, enabling timely and appropriate care." (PMID 33585199, 2020). "Germline mutations in the RNA helicase DDX41 predispose to increased lifetime risks of myeloid neoplasms with disease often occurring later in life which presents challenges for germline recognition." (PMID 33585199, 2020). "In summary, comprehensive molecular analyses using SNP-A karyotyping, WES and targeted sequencing revealed recurrent somatic mutations involving CSNK1A1 and G3BP1 in the CDR and DDX41 in the CRR in myeloid neoplasms with the del(5q)." (PMID 28031539, 2017). "One of the most recently described inherited susceptibility loci for myeloid neoplasms, DDX41 germline mutations, located on chromosome 5q, are associated with autosomal dominant familial MDS/AML." (PMID 27248996, 2016). "DDX41 mutations result in an increased lifetime risk of myeloid neoplasms including MDS, AML, and chronic myeloid leukemia (CML), although notably after a long latency, with an average age of disease onset of 61 years." (PMID 27248996, 2016). "DDX41 mutations are associated with myeloid neoplasms, including myelodysplastic syndrome (MDS) and acute myeloid leukemia (AML), and missense mutant R525H is seen in 67% of patients; however, its molecular pathogenesis is unknown." (PMID 41816910, 2026). "For the purpose of precisely characterizing the prognostic significance of DDX41 mutations in myeloid neoplasm patients and to clarify the associations between DDX41 mutations and the clinicopathological features of myeloid neoplasms, we conducted a meta-analysis." (PMID 40257479, 2025). "Deleterious germline DDX41 variants constitute the most common inherited predisposition disorder linked to myeloid neoplasms (MNs), yet their role in MNs remains unclear." (PMID 40764304, 2025). "In patients with myeloid tumors, hereditary and sporadic mutations of DDX41 have been identified." (PMID 40257479, 2025). "Pathogenic mutations in DDX41 are detected in around 5% of instances of myeloid neoplasms." (PMID 40257479, 2025). "Though one of the most prominent predisposition genes for myeloid malignancies is the DDX41 mutation, the precise implications of DDX41 mutations in myeloid malignancies remain unclear." (PMID 40257479, 2025). "DDX41 deficiency leads to G4 accumulation, causing genome instability, ribosomal defects, and cGAS-mediated cell death, impairing erythropoiesis and contributing to myeloid neoplasm pathogenesis." (PMID 40764304, 2025). "It is presently unknown how precisely these co-mutations in DDX41-mutated myeloid malignancies work." (PMID 40257479, 2025). "In conclusion, we found that OS for myeloid neoplasms is significantly impacted by DDX41 mutations." (PMID 40257479, 2025). "Mutation of DDX41 has been widely reported in various types of myeloid neoplasms." (PMID 40257479, 2025). "The stepwise exclusion of included studies did not result in any significant differences, suggesting that the individual contributions of each study were inconsequential with respect to the stability of the relationship between DDX41 mutations and OS in patients diagnosed with myeloid neoplasms." (PMID 40257479, 2025). "DDX41 mutation related to prevalence of different myeloid neoplasms." (PMID 40257479, 2025).